RYR1 (ryanodine receptor 1)
Diseases named in the same sentence as RYR1 in open-access papers (continued):
Sharing a sentence is not in itself a finding about the gene and the disease.
myopathies (continued). "Since most core diseases are caused by RYR1 variants, it may also be another target in excitation‐contraction coupling for the studies of ACTN2‐related myopathy." (PMID 34170073, 2021). "Other clinical information, including myopathy phenotype, were not described in this study, though prediction software suggests many of these RYR1 variants are likely pathogenic, or VUS with damaging predictions." (PMID 34528764, 2021). "For RYR1-related myopathies specifically, the next step is to test p38 blocking treatments in mice." (PMID 32223895, 2020). "The function of RYR1 is related to inner cell Ca2+ flow regulation, the dysfunctions of this factor could lead to heart conditions, myopathies, and neurodegenerative disease, how this gene could affect PA development needs to be further investigated." (PMID 32528411, 2020). "Such an “evolutionary pipeline” approach was reported recently to identify small molecules that might be useful for treating RYR1‐related myopathies." (PMID 32857472, 2020). "This suggests p38 blockers may have potential as a treatment for RYR1-related myopathies in mammals." (PMID 32223895, 2020). "To conclude, this study demonstrates that RyR1 reduction is sufficient to induce a myopathy." (PMID 33176865, 2020). "We show that few weeks after induction, the amount of RyR1 protein reached 50% of initial level, and the mice developed a progressive myopathy, which recapitulates the main features observed in patients affected with Dusty Core Disease and with a similar RyR1 reduction." (PMID 33176865, 2020). "Importantly, in a very recent randomized, double-blinded, placebo-controlled trial, NAC was shown to be safe and well-tolerated in individuals with ryanodine receptor 1-related myopathies." (PMID 32197453, 2020). "NAC has also been evaluated in individuals with ryanodine receptor 1-related myopathies." (PMID 32560255, 2020). "NGS was performed according to standard protocols and showed no pathological mutations in 251 myopathy-related genes including RYR1, POLG and other nuclear encoded mitochondrial genes." (PMID 31991853, 2020). "Although hyper-methylation-induced RyR1 silencing was unveiled in skeletal muscle of patients with recessive core myopathies, our knowledge concerning the epigenetic regulation in RyR1-mediated adipogenesis and myogenesis within skeletal muscle remains limited, let alone ATP2B3." (PMID 33308295, 2020). "It is possible that repurposing existing drugs could benefit people with RYR1-related myopathies, but trialing treatments takes time." (PMID 32223895, 2020). "Among these chronic onset cases, DM1&2 (n = 1), LGMD (n = 5), RYR1 (n = 1) and MtM (n = 1) myopathies were thought to be the initial diagnosis but genetic testing was negative or created uncertainty with a variant of unclear significance in large gene panel testing." (PMID 33364599, 2020). "In addition to myopathy, other clinical phenotypes attributed to RYR1 variations include rhabdomyolysis-myalgia syndrome and intermittent periodic paralysis." (PMID 32381029, 2020). "Age is also identified as a factor of relevance to manifestation of RyR1-related myopathies." (PMID 32174957, 2020). "The T4826I mutation in the transmembrane domain of RYR1 is associated with MHS without core myopathy in humans." (PMID 31874912, 2019). "What are the pathological mechanisms of non-RYR1 core myopathies?" (PMID 31874912, 2019). "Finally, our results represent an emerging evidence in RYR1-recessive myopathies, but restricted to a specific study population, restricted in a monocentric study." (PMID 30611313, 2019). "Nevertheless, this somewhat limits the use of Ryr1+/− mice for core myopathy research." (PMID 31874912, 2019). "Results collected in mice carrying human mutations linked to CCD in humans have provided evidence that oxidative stress may represent a pathophysiological mechanism in CCD and other RYR1-related myopathies." (PMID 31191425, 2019).
myopathies (continued). "DuCD represent the last end morphological spectrum of RYR1- related myopathies." (PMID 30611313, 2019). "Absence of clinical evidence of myopathy in the family members carrying only one of the two mutation in the RYR1 gene and evidence of central core in the proband carrying two mutations agrees with a recessive form of CCD." (PMID 31191425, 2019). "Importantly, disease-causing mutations or variants in RYR1 and CACNA1S have been found to be more frequent in statin myopathy patients than controls." (PMID 31861911, 2019). "The age at onset of RYR1-related myopathies varies from infancy to adulthood." (PMID 31165076, 2019). "Finally, dusty cores should be considered the unifying morphological feature among DuCD spectrum disorder and represent the morphological signature of RYR1-recessive myopathy, even when detected in only few fibres." (PMID 30611313, 2019). "Recently, both dominant and recessive families with a Cav1.1-related myopathy have been described, suggesting further phenotypic overlap between RYR1 and Cav1.1 dysfunction and a continuum between myopathic and episodic phenotypes due to mutations in these genes." (PMID 29298851, 2018). "One patient with myopathy NOS was genetically diagnosed with RYR1 myopathy." (PMID 30356714, 2018). "In RYR1-related myopathy mice, IM fiber abnormalities prior to EM fiber alterations imply that the IM fiber is friable and is a primary pathological feature in this degenerated myopathy." (PMID 30219099, 2018). "The other 2 patients had an episodic phenotype without myopathy and were either heterozygous for or compound heterozygous for RYR1 missense mutations (putatively) implicated in the MH trait, suggesting tentative genotype-phenotype correlations." (PMID 29298851, 2018). "In spite of the broad clinical features of RyR1-related myopathies, the pathology is dominated by ultrastructural derangement of myofibres resulting in the focal loss of mitochondria in either a single longitudinal central core or multiple smaller cores (multi-minicores)." (PMID 29701772, 2018). "To develop interventions for RyR1 myopathies arising from RyR1 mutations that do not produce Ca2+ leak, we created mice with the I4895T mutation (equivalent to I4898T in humans)." (PMID 28337975, 2017). "In our study, 4PBA dramatically improves muscle function and increases muscle fibre size in the IT mice at all ages tested, strongly supporting our hypothesis that this RyR1 myopathy is an ER stress/UPR disorder." (PMID 28337975, 2017). "This may also be the case for muscle weakness observed in individuals with RyR1 myopathies under CCD and S-nitrosylation." (PMID 27855725, 2016). "RYR1 variants were identified in 3 severe statin myopathy cases, 1 mild myopathy statin individual, 8 patients with non-drug-induced myopathy and no variants were present in controls." (PMID 26238698, 2015). "However, it is of note that marked autophagy abnormalities have been observed in mice following induced reduction of the DHPR receptor, a secondary feature also in recessive RYR1-related myopathies." (PMID 25566070, 2014). "In addition, though the age at presentation of recessive RYR1 myopathies is variable, in a recent series all presented before age 10 years." (PMID 25476234, 2014). "Interestingly, other aspects characteristic of autosomal recessive RYR1 related myopathies, such as the presence of cores and ocular involvement, were not present." (PMID 23894444, 2013). "Therefore RYR1 related myopathy should be considered in wide variety of clinical and pathological presentation in childhood myopathies." (PMID 23894444, 2013). "More recently, several additional atypical RYR1-related myopathies have been reported." (PMID 23894444, 2013). "The discovery of RYR1 mutations in cases of non-core myopathy is a relatively recent phenomenon, and the relative prevalence of such cases has been uncertain." (PMID 23919265, 2013).
myopathies (continued). "The β-agonist salbutamol has been recently studied as a pharmacological agent in the treatment of RYR1-related myopathies with encouraging results, however, results of this pilot study will have to be validated in a larger randomized controlled trial as a basis for future recommendations." (PMID 17631035, 2007). "Therefore, its clinical relevance, particularly with regard to RYR1-associated myopathies or MND, is not yet known." (PMID 41180248, 2025). "Although, our description of two functionally distinct classes of RyR1 channels in TM muscle falls short of determining their relative role in disease pathogenesis, these results should be taken into consideration in the development of new therapeutic interventions for RyR1-related myopathy." (PMID 37670077, 2023). "If undesired RyR1 activation gives rise to statin myopathy, the design of new statin drugs with reduced side effects would require that the functional groups of the molecule which cause RyR1 activation can be removed without disturbing its affinity for HMG‐CoA reductase." (PMID 35703154, 2022). "On the other hand, RYR1 mutations found in patients with CCD may be present in individuals with MH susceptibility but no sign of myopathy." (PMID 35980353, 2022). "Thus far, MYH1 has not been associated with RYR1 mutation-associated myopathies, but it has been found in studies on other muscle diseases that MYH1 mutations in humans and horses are closely related to recurrent rhabdomyolysis." (PMID 35692882, 2022). "Indeed, despite in the last years the list of RYR1‐related myopathies has been further expanded with the inclusion of novel histological findings such as dusty cores and protein aggregate inclusions, RYR1 mutations have never been identified in patients with TAM." (PMID 35666680, 2022). "However, the finding that cerivastatin is the strongest activator of RyR, at all cytosolic [Ca2+], including sub‐activating levels, supports the hypothesis that inappropriate activation of RyR1 may be the first step leading to statin‐induced myopathy." (PMID 35703154, 2022). "At that time, we were not aware that these lesions could represent a hallmark of RYR1-recessive myopathy, as 7 cases represented a small cohort and it could had been an atypical variability of findings in RYR1-recessive patients." (PMID 30611313, 2019). "RYR1 mutations can cause late-onset atypical PP both with and without associated myopathy." (PMID 29298851, 2018). "Moreover, by rendering an overall adaptive function most likely for the up-regulation of IP3Rs, the hypothesis of IP3-mediated Ca2+ overload as a ruling pathomechanism in RyR1-related myopathies is implausible." (PMID 29701772, 2018). "In addition, indirect or secondary RyR1 malfunction is also present in other myopathies not related to RyR1 mutations." (PMID 26793121, 2015). "Thus in a series of 118 patients with RYR1-related recessively inherited myopathies from four recent reports, 61.5% of the cases had a truncating/in frame deletion/splice site mutation in combination with a missense mutation and 38.1% harboured two missense mutations." (PMID 25476234, 2014). "The genetics of RYR1-related myopathies are not infrequently complex, occasionally with two clearly pathogenic RYR1 mutations occurring on the same allele or running independently in the same family, possibly accounting for the wide phenotypical variability and variable penetrance." (PMID 25566070, 2014). "Once ascertainment bias is removed (i.e. a historical skewing toward RYR1 mutation identification in core myopathies because these were the first RYR1 myopathies identified), it is possible that non-core myopathies ultimately account for more than 50% of recessive RYR1 disease." (PMID 23919265, 2013). "However, a potential caveat to this assertion is a reverse bias created by the fact that some patients with core myopathy (particularly central core disease) are assumed to have RYR1 mutations and thus not confirmed at the genetic level." (PMID 23919265, 2013).
myopathies (continued). "RYR1-related CNM often presents as a mixed phenotype between CNM and core myopathies, with the presence of multiple central nuclei and core-like structures with no limited boundaries." (PMID 35980353, 2022). "Of the DNM2‐CNM patients, 61% had family members with a diagnosed myopathy; in MTM1 and RYR1 patients this was the case in 50% and 44%, respectively." (PMID 34463354, 2021). "In fact, no dusty cores were observed among 154 muscle biopsies of dominant RYR1- and 10 of MYH7-related myopathies examined in our lab." (PMID 30611313, 2019). "The roles of other select myopathy genes (CPT2, RYR1, CACNA1S) are covered in more detail in the relevant sections below." (PMID 31861911, 2019). "However, the consequences of mutations on RyR1 expression and function vary wildly in specific cases, thus whether IP3R-mediated Ca2+ signals operate as an overall adaptive mechanism in core myopathies remains to be studied." (PMID 29701772, 2018). "The muscle biopsy of our index patient showed pathological alterations including enhanced central agglomeration of NADH and SDH in the muscle fibers, compatible with RYR1-related myopathy, but no typical cores or multiminicores." (PMID 39409197, 2024). "For electrophysiological studies of channelopathies, including RyR1-related myopathies, cells without muscle-specific proteins can be advantageous, and HEK cells are commonly used." (PMID 39425123, 2024). "There is currently no FDA-approved treatment for RYR1- related myopathies (RYR1-RM), although it is worth noting the RYR1 antagonist, dantrolene, is approved for use during MH events to attenuate excessive ER/SR calcium release." (PMID 35698232, 2022). "In a large cohort including 106 cases of recessive RYR1- related myopathies, nearly 50% of the cases had non-core myopathy, and hypomorphic variations were more frequently observed in non-central core myopathies." (PMID 35693006, 2022). "EHS and ERM occur more often in patients with known or not yet diagnosed myopathy, especially RYR1-related myopathies, without any pharmacological trigger." (PMID 36360420, 2022). "Patients with recessive RYR1- related non-core myopathies usually had a combination of a null variation and a missense variation." (PMID 35693006, 2022). "Despite this, in the largest review of 106 RYR1-recessive cases, up to 40% of patients did not fill these categories and were classified as Atypical Core Myopathy or different nonspecific histopathological groups." (PMID 30611313, 2019). "Although core-like structures were seen, they were not felt to be typical of central core disease, a common RYR1-related myopathy, and no definitive diagnosis was reached." (PMID 29298851, 2018). "Muscle biopsy and muscle respiratory chain enzymes were normal, investigations to exclude selenoprotein-related myopathy (SEPN1-gene) and ryanodine receptor 1 (RYR1-gene)- related myopathy have been performed and showed no pathology." (PMID 28328806, 2017). "4PBA, however, did not restore the amplitude of SR Ca2+ release via RyR1, suggesting that reduced Ca2+ release is not the primary driver of the myopathy." (PMID 28337975, 2017). "Patients with RYR1-related CNM show a marked tendency to improve over time, even following an initially severe presentation, a feature also in other recessive RYR1-related myopathies that remains currently unexplained." (PMID 25566070, 2014). "However, chronic RyR1 Ca2+ leak causes mitochondrial overload and dysfunction as evidenced by the cores (regions lacking mitochondria) that characterise RyR1 myopathies in humans." (PMID 37986616, 2023). "There are currently no FDA approved treatments for RYR1-related myopathies (RYR1-RM)." (PMID 35698232, 2022).
myopathies (continued). "However, these histopathologic features are not unique to RYR1-RM, can be dynamic over time, may vary based on biopsy site, and may be absent when biopsy is performed at an early age or reflect a consequence of the gene dose (heterozygous = MH susceptibility versus homozygous = clinical myopathy)." (PMID 33190635, 2020). "This type of pipeline could identify new treatments, not just for RYR1-related myopathies, but for other diseases that involve genes or proteins that are similar across species." (PMID 32223895, 2020). "To date, arrhythmia has never been reported in cases of congenital RYR1-related myopathy." (PMID 31856875, 2019). "Moreover, lifestyle habits, such as excessive exercise regimens that induce SR Ca2+ leak via RyR1 FKBP12 dissociation, might also reveal overt myopathy with statin treatment." (PMID 31468006, 2019). "Since both authors make valid points, whether or not the absence of triadin results in a RyR1 myopathy has yet to be determined." (PMID 27855725, 2016). "At this time, no specific treatments are available for any RYR1-related myopathy, though modifying oxidative stress may be one therapeutic avenue." (PMID 23919265, 2013). "Overall, the clinic and histopathology of RYR1-related ARCNM mostly represent a continuum between classical CNM and core myopathies, with core-like structures and internal rather than central nuclei." (PMID 34768808, 2021).